TF (transferrin)
Diseases named in the same sentence as TF in open-access papers (continued):
Sharing a sentence is not in itself a finding about the gene and the disease.
anemia (continued). "A situation of low serum iron associated with low transferrin saturation and high serum ferritin, with low total iron-binding capacity, is very suggestive of anemia of chronic diseases." (PMID 32481481, 2020). "The significant factors associated with moderate-severe anaemia at 12 months were: female gender, allograft function, recent rejection, recent infection, transferrin saturation < 10% and proteinuria." (PMID 30290796, 2018). "In multivariable logistic regression analysis, the significant factors associated with moderate-severe anaemia at 6 months were: female gender, allograft function, transferrin saturation < 10%, recent treatment with IVIG and proteinuria." (PMID 30290796, 2018). "Lower kidney function, female gender, transferrin saturation below 10% and proteinuria were associated with moderate-severe anaemia at both time points." (PMID 30290796, 2018). "Systemic levels of transferrin differently respond to anemia depending on its cause, being elevated in IDA but normal/decreased in ACD." (PMID 29226154, 2017). "This sequestration of iron is accountable for the condition known as anemia of inflammation, which is also associated with a rise in ferritin and decreased iron, transferrin, and transferrin saturation." (PMID 29143766, 2017). "The serum transferrin is measured for various reasons: to determine the cause of anemia, to evaluate iron metabolism (for example, in iron deficiency anemia) and to determine the iron-carrying capacity of the blood." (PMID 27651883, 2016). "Severe mutations in the transferrin gene lead to atransferrinaemia and have been determined to cause microcytic anaemia accompanied by hepatic accumulation of iron in humans and mice." (PMID 27332551, 2016). "In spite of the increased EPO blood levels, anemia persisted and was linked to low serum iron and transferrin levels, while serum interleukin (IL)-6 and high sensitivity C-reactive protein (hs-CRP) levels showed the absence of systemic inflammation." (PMID 25867633, 2015). "In the CRF rats, despite the increased EPO serum levels, anemia persisted and was linked to low serum iron and transferrin levels, while serum IL-6 and hsCRP levels showed the absence of systemic inflammation." (PMID 26712750, 2015). "Introduction of this method was expected to negate many of the factors attributed to gender (e.g., pregnancy, oestrogens and anaemia), since they can cause variations in total transferrin concentrations." (PMID 24885510, 2014). "Obesity is characterized by chronic, low-grade, systemic inflammation, which, in turn, has been associated with anemia of chronic disease specifically, elevated serum ferritin and low serum iron, transferrin saturation (TS), and hemoglobin." (PMID 24665367, 2014). "In a non-malarious area the diagnostic sensitivity and predictive value of ZPP for evaluating iron depletion and risk of anaemia in pregnancy compared favourably to those of ferritin and transferrin saturation measurements.." (PMID 22846214, 2012). "Raised saturation of transferrin used to assess risk of tissue iron loading (e.g., in hemochromatosis or iron-loading anemias)." (PMID 22254098, 2011). "Additionally, the chronic inflammatory state in CKD patients can affect the glycosylation modification of transferrin (TF), leading to changes in the proportion of TF variants, which in turn impairs iron transport efficiency and exacerbates anemia." (PMID 41311841, 2025). "However, there were no significant causal associations between total iron-binding capacity (OR = 1.207, 95%CI: 0.961–1.515, p = 0.106), transferrin saturation (OR = 0.891, 95%CI: 0.776–1.024, p = 0.103), and anemia risk." (PMID 41156473, 2025). "A previous study had indicated that vitamin C could regulate transferrin iron uptake and that vitamin C deficiency might induce anemia." (PMID 41383345, 2025).
anemia (continued). "Also, there were still no significant causal associations between total iron-binding capacity (OR = 1.071, 95%CI: 0.897–1.280, p = 0.447), transferrin saturation (OR = 1.008, 95%CI: 0.860–1.181, p = 0.920), and anemia risk after removing the outliers." (PMID 41156473, 2025). "Assessing serum iron levels and transferrin saturation percentage could have provided valuable insights into anemia secondary to GI blood loss." (PMID 39057990, 2024). "Thus, indiscriminate iron supplementation to treat anaemia triggered by inflammation can override this host‐defense mechanism and lead to increases in the concentration of non‐transferrin bound iron, which has been linked to increased morbidity and mortality." (PMID 34624171, 2024). "A second cluster involved multiple markers of anemia (transferrin and serum iron), strongly associated with markers of one-carbon metabolism (B12, folate), liver metabolism (GGT, ALT, AST, LDH), ADP-ribosylation factors 1 and 3 (ARF1, ARF3), and the structural protein desmatin (DMTN)." (PMID 38543504, 2024). "Therefore, this study is considered a vital report in real-life clinical practice showing the association between transferrin saturation and patient prognosis in treating anemia with erythropoiesis-stimulating agents in patients with CKD." (PMID 38941000, 2024). "Anemia during the acute phase of naturally infected E. canis was reported to be associated with altered oxidative status, low iron levels, and high levels of both ferritin and TF." (PMID 36855344, 2023). "Proteinuria was associated with urinary loss of both iron and TF which may contribute to anemia in CKD." (PMID 36855344, 2023). "Both gave significant differences in anemia prevalence, mean [Hb], transferrin, and hepcidin according to iron status; in each case the associations were similar: iron-deficient patients had lower [Hb], higher transferrin and lower hepcidin." (PMID 35710500, 2022). "In addition, when there are both HF and a decline in renal function, the kidney reduces EPO production and increases urinary loss of serum EPO and transferrin, resulting in anemia's progression." (PMID 35581275, 2022). "The rationale behind this could be that an excess of chromium that binds to transferrin may cause anemia." (PMID 34202347, 2021). "However, it can reduce the expression of transferrin by inhibiting hepcidin overexpression caused by inflammation, promoting the outward transfer of intracellular iron and thus improving anemia." (PMID 34663434, 2021). "In HIV patients, low hemoglobin levels were associated with higher interferon and lower transferrin, which may cause anemia in these patients." (PMID 32899810, 2020). "Since, transferrin is associated with anemia which is a well known characteristic feature of MM, it could be a potential protein marker for MM." (PMID 33585190, 2020). "Generally, anemia is associated with low iron function in available transferrin." (PMID 31105509, 2019). "Gender-related difference in transferrin levels and transferrin saturation associated with TMPRSS6 rs855791 variants in patients with ESRD-related anemia is potentially clinical relevant, but the pathophysiological mechanism should be examined in extensive studies." (PMID 30984307, 2019). "Elevated ferritin level, serum transferrin, transferrin receptor (TfR), TIBC, erythrocyte sedimentation rate, and C-reactive protein concentrations, and reduced serum iron concentrations and transferrin saturation are usually associated with anemia of chronic disease." (PMID 30237895, 2018). "Interestingly, we found some differences between CD and UC concerning transferrin; it was generally more closely associated with oxidative stress and more loosely with inflammation (except for hsCRP and IL-1) and anemia/nutritional status in CD." (PMID 29226154, 2017). "We examined transferrin association with indices of nutritional status and anemia." (PMID 29226154, 2017).
anemia (continued). "However, its utility as a differentiating marker in IBD-associated anemia is questioned since transferrin concentration varies also in response to inflammation and malnutrition." (PMID 29226154, 2017). "Transferrin is associated with anemia/malnutrition in UC while with oxidative stress in CD." (PMID 29226154, 2017). "The blood transferrin is used to determine the cause of anemia and examine iron metabolism." (PMID 25789206, 2015). "Consistent with a critical role for PICALM in iron homeostasis, PICALM-deficient mice suffer from severe anemia and poor erythroid development and, at the cellular level, show reduced transferrin uptake; iron supplementation ameliorates some aspects of PICALM deletion." (PMID 24618820, 2014). "Transferrin saturation (Tsat) may be used to diagnose iron deficiency anemia." (PMID 37337504, 2023). "However, sex-stratified associations of age with ferritin, transferrin, and transferrin receptors after excluding the potential effect of anemia remain unknown." (PMID 36091521, 2022). "Furthermore, the commonly used antiarrhythmic digoxin has anticholinergic properties and may predispose to development of anemia mainly disturbing transferrin signaling and iron storing." (PMID 34682773, 2021). "In addition, lymphopenia, elevated levels of the immune biomarkers C-reactive protein (CRP), interleukin 6 (IL-6), neopterin or ferritin, low levels of the iron transfer protein transferrin or testosterone deficiency and anemia were shown to be associated with an adverse outcome." (PMID 34677368, 2021). "Similarly, transferrin saturation showed significant association with anemia." (PMID 32246050, 2020). "NNVCP binding to hemoglobin and transferrin may cause anemia upon grouper infection with NNV." (PMID 32899810, 2020). "Of 604,936 patients who underwent any anemia-related laboratory testing, only 5.1%, 0.4%, and 15.1% had their serum ferritin, transferrin saturation, and serum iron measured, respectively." (PMID 41931205, 2026). "Elevated transferrin (aOR 2.05; 95% CI: 1.76–2.39; p < 0.001) and TIBC (aOR 2.41; 95% CI: 2.02–2.88; p < 0.001) were also associated with anemia." (PMID 41458907, 2025). "Conventionally, the diagnosis of IDA was based on the presence of microcytic hypochromic anemia and abnormal iron status, such as transferrin saturation <10% and serum ferritin level <12 ng/mL." (PMID 40426817, 2025). "Within 6 months from incident anemia, ferritin and transferrin saturation were tested in 44% overall and 65% of severe cases." (PMID 40797259, 2025). "Laboratory testing for ferritin, transferrin, transferrin receptor and CRP can help distinguish between inflammation-induced anemia and iron-deficiency related anemia but rarely allows for a definitive diagnosis in intermediate cases." (PMID 40636681, 2025). "Our focus was on “serum ferritin and transferrin saturation” values, which are vital in diagnosing anemia." (PMID 40530793, 2025). "Other anemia-related parameters such as hematocrit, serum ferritin, or transferrin saturation would indeed offer a more comprehensive understanding of anemia etiology." (PMID 40648519, 2025). "The heightened incidence of severe anemia in our HFmrEF subgroup may reflect referral bias toward decompensated patients or a unique inflammatory milieu in HFmrEF, as suggested by recent biomarker analyses demonstrating altered transferrin saturation and proteomic associations in HF." (PMID 40870930, 2025). "TIBC is used in conjunction with other iron studies (serum iron, ferritin, transferrin saturation) to assess iron status and differentiate types of anemia." (PMID 40486642, 2025). "For example, total cholesterol, LDL, and HDL values for the diagnosis of heart disease, TSH, and ft4 values for the diagnosis of goiter disease, and ferritin and transferrin saturation percentage values for the diagnosis of anemia can be evaluated together." (PMID 40530793, 2025).
anemia (continued). "As a divalent metal cation, the cobalt ion competes with the iron ion for binding to transferrin and ferroportin, disrupting systemic iron homeostasis—a fundamental mechanism in anemia pathogenesis." (PMID 40969594, 2025). "Specifically, we observed a downregulation of hepatic hepcidin and upregulation of Fpn and transferrin on day 12 p.i, coinciding with increased erythropoietic drive and anemia." (PMID 40871363, 2025). "Increased ferritin levels paired with decreased serum iron and transferrin levels can indicate anemia of inflammation." (PMID 40362718, 2025). "When patients were stratified by anemia (Hb < 12 g/dL in women and Hb < 13 g/dL in men), a significant improvement of transferrin saturation was observed only in anemic patients (from 13.3 ± 5.8% to 20.2 ± 8.1%, p = 0.012)." (PMID 38732502, 2024). "We obtained the following parameters: serum creatinine and urea; the inflammation markers CRP (C-reactive protein) and IL-6 (interleukin-6); and the anemia markers complete blood count, serum ferritin, and transferrin saturation (TSAT)." (PMID 39200365, 2024). "The impact on transferrin saturation was more pronounced in the subgroup of NDD-CKD patients with anemia, likely because the higher iron demand for stimulating erythropoiesis prevails over the need of replenishing iron stores." (PMID 38732502, 2024). "The paradoxical nature of anemia, often microcytic with low transferrin saturation and hyperferritinemia, is usually present in several cases." (PMID 39165621, 2024). "ACD usually presents with mild normocytic anemia, reduced circulating iron concentrations, normal or reduced transferrin saturation, and normal or increased ferritin levels." (PMID 39408004, 2024). "Functional ID is a consequence of inflammation and is characterized by normochromic normocytic anemia with normal to increased serum ferritin levels and low transferrin values." (PMID 36986429, 2023). "In the current study, significantly higher concentrations of transferrin were found in patients with anaemia in the course of UC compared to CD (2.58 ± 0.90 g/L vs. 2.15 ± 0.82 g/L; p = 0.037)." (PMID 37048531, 2023). "Another important parameter in the differential diagnosis of anaemia in IBD patients is transferrin saturation (TfS), which is an indicator of iron availability for haematopoiesis." (PMID 37048531, 2023). "Renal failure, in which EPO production is reduced, and the presence of proteinuria with possible loss of transferrin and EPO represent other causes of anemia." (PMID 37374094, 2023). "A complex laboratory assessment, including the determination of hepcidin and transferrin saturation, is important for the full picture of anaemia in the course of IBD." (PMID 37048531, 2023). "At day 60, a Hb rise was observed in both groups (+ 3.6 ± 1.5 g/dL; p < 0.01), 81% experienced correction of anemia (Hb ≥ 12 g/dL), 36% achieved a ferritin concentration ≥ 30 ng/mL (p < 0.05), and 54% a transferrin saturation (TSAT) ≥ 20% (p < 0.01)." (PMID 37198549, 2023). "Again, it is known that anemia is relatively prevalent in the elderly, and anemia itself was probably the reason the physicians tested for ferritin, iron and transferrin saturation." (PMID 37511109, 2023). "It reduces the flow of iron into the circulation, where it can be used by erythroblasts thanks to the binding of TfR1 with transferrin, which leads to anemia in chronic inflammation." (PMID 36986181, 2023). "Although pre-albumin and transferrin have been found to be prognostic for mortality, their turnover rate, half-life, and potential interference by inflammation and anemia substantially limit their universal use." (PMID 36771356, 2023). "An elevated transferrin saturation can be an indicator of iron overload, such as due to haemochromatosis, multiple transfusions and iron-loading anemias." (PMID 36823529, 2023).
anemia (continued). "Cancer-induced anemia is commonly characterized by decreased serum iron concentrations and transferrin saturation despite sufficient iron stores, known as functional iron deficiency anemia (FIDA)." (PMID 37208766, 2023). "We showed that all anemia-related biochemical variables were significantly different across the tertiles of serum vitamin D levels in the pregnant women, except for transferrin saturation." (PMID 37111023, 2023). "Patients were screened for anemia (< 12.0 g/dL in women and < 13.0 g/dL in men) and ID (either absolute [ferritin < 30 μg/L] or functional [ferritin ≥ 30 μg/L + transferrin saturation < 20% + C-reactive protein > 5 mg/L])." (PMID 37434251, 2023). "A steady decline in serum transferrin levels indicates the anemia is being cured and a lesser amount of iron is needed by the body." (PMID 37384107, 2023). "It is also important to fully understand the microcytic hypochromic anemia discovered in the mice, including analysis of the factors involved, such as transferrin and ferritin, to give a more precise understanding of its nature." (PMID 37713409, 2023). "Significantly higher concentrations of transferrin were observed in patients with anaemia in the course of UC compared to CD (2.58 ± 0.90 g/L vs. 2.15 ± 0.82 g/L; p = 0.037)." (PMID 37048531, 2023). "A decline in serum transferrin is favorable for anemic subjects because it indicates that anemia is being rectified and lesser iron is needed subsequently by the body." (PMID 35844906, 2022). "The studies included in this review used different indicators of iron status and anaemia (haemoglobin, serum ferritin, and serum transferrin) as well as different concentrations of iron fortification in the intervention milks." (PMID 36501090, 2022). "When predictors of survival were analyzed in the group of patients with available serum iron parameters, age, hemoglobin, CRP, anemia etiology, ferritin and transferrin were predictors of survival." (PMID 35895618, 2022). "On the other hand, as soon as anemia starts to improve, serum transferrin levels of an individual are declined." (PMID 36451738, 2022). "Anemia assessments were analyzed by either ferritin levels alone (10.1%) or with additional transferrin saturation (16.2%)." (PMID 36415561, 2022). "Transferrin saturation and haemoglobin levels were lower in all groups, as compared to the Dutch reference while the prevalence of anaemia varied between groups, ranging from 4 % (Dutch) to 28 % (Surinamese-Creole)." (PMID 35720171, 2022). "Apart from hemoglobin concentration measurements, several biological markers such as ferritin, transferrin and sTfR can be useful proxies for assessing changes in body iron status and anemia." (PMID 35245314, 2022). "For the present study a ferritin >100 μg/L and transferrin saturation <20% have been used to categorize preoperative anemia as AI." (PMID 35895618, 2022). "Among those findings we can mention the higher D Dimer the lower transferrin that are common in anemia of chronic diseases, and the higher and abnormally elevated CRP and ferritin levels all observed in the asplenia/hyposplenism group." (PMID 36105295, 2022). "At birth, she presented with severe microcytic anemia and intense erythroblastemia, together with high serum iron levels, elevated transferrin saturation and normal serum ferritin." (PMID 35457224, 2022). "4.Aim at a transferrin saturation between 30% and 50% and a ferritin level >300 mcg/l to 800 mcg/l in pregnant dialysis patients with anemia." (PMID 36506226, 2022). "Children with anemia in AI had very low levels of SI, transferrin and sTfR, with inverse correlations to serum hepcidin." (PMID 35177695, 2022). "Metabolic acidosis, anaemia with low transferrin levels, hyperuricemia and hyperkalemia were highly prevalent in our patients, including those with early CKD, and they were strongly associated with advanced CKD." (PMID 36121812, 2022).